MIF (macrophage migration inhibitory factor)
Diseases named in the same sentence as MIF in open-access papers (continued):
Sharing a sentence is not in itself a finding about the gene and the disease.
lung cancer (continued). "To investigate the potential mechanism of brain metastasis (BM) in NSCLC, we found that MIF was upregulated in lung cancer compared to adjacent tissues by analyzing the public NSCLC transcriptomic data via the LUNG CANCER EXPLORER website." (PMID 38685050, 2024). "CD74 is a type II transmembrane protein with various biological functions that promote the angiogenesis of lung cancer cells when co-expressed with macrophage migration inhibitory factor (MIF)." (PMID 37745301, 2023). "Previous studies have reported that MIF is overexpressed in various tumours, such as prostate, breast, gastric and lung cancer." (PMID 37784249, 2023). "Our analysis also identified four highly significant differentially expressed genes in lung cancer, namely, MIF, CLEC3B, FCN3, and EMCN." (PMID 37359381, 2023). "Our analysis revealed a significant interaction between the core metabolite citric acid, which is involved in the Citric acid cycle, and the differentially expressed gene MIF in lung cancer." (PMID 37359381, 2023). "Our analysis identified four highly significant differentially expressed genes in lung cancer, comprising MIF, CLEC3B, FCN3, and EMCN." (PMID 37359381, 2023). "We employed mouse Lewis lung carcinoma cell line and human lung cancer cell line H460, which expressed CXCR2 on the surface and secreted CXCR2-associated chemokines, such as CXCL1, CXCL2, CXCL5 and MIF." (PMID 33814009, 2021). "Our CRC patient study as well as patient studies of lung cancer and colon carcinomatosis indicate that MIF/CD74 co-expression corresponds to an even worse prognosis." (PMID 33542244, 2021). "Differently, high levels of MIF were correlated with reduced drug responsiveness and with poorer outcomes in lung cancer patients." (PMID 32155795, 2020). "In summary, cisplatin resistant lung cancer cells not only showed an increased self-renewal ability but also promoted M2 polarization of TAMs via the secretion of MIF." (PMID 31036057, 2019). "MIF overexpression has been observed in a number of human cancer types, and several reports support MIF’s role in protection from apoptosis in vitro, including in models of lung cancer and cervical adenocarcinoma." (PMID 29864117, 2018). "Increased circulating MIF levels are correlated with high tumor burden and metastasis in e.g. prostate cancer, lung cancer, colon cancer and ovarian cancer." (PMID 27636991, 2016). "In the current study, we discovered that MIF secretion can be induced by ionizing radiation (IR) and other DNA damaging agents in renal, breast, and lung cancer cells." (PMID 26741693, 2016). "During the course of this work, another study targeting MIF in lung cancer cells also demonstrated efficient knockdown of MIF using duplexes identical to the MIF-25 targeting sequence." (PMID 25168062, 2014). "The human H460 lung cancer cell-line was treated with an optimally determined dose of 50 pmol/ml MIF siRNA, following which cell proliferation, cell cycle and apoptosis were analyzed." (PMID 23522304, 2013). "High expression of MIF in lung cancer patients predicts a worse prognosis for disease free and overall survival." (PMID 23522304, 2013). "In vitro inhibition of MIF or its receptor resulted in reduced production of angiogenic CXC chemokines by lung cancer cells." (PMID 19602232, 2009). "In lung cancer specimens MIF staining was noted to be more intense and seen in the nuclei of a large portion of the specimens." (PMID 17650334, 2007). "MR-PRESSO outlier testing validated the significant MR findings, except for monocyte chemoattractant protein-3 (MCP-3) in lung cancer (including different pathologic types), and macrophage migration inhibitory factor (MIF) and IL-5 in small-cell lung carcinoma, where limited SNPs were available." (PMID 38957317, 2024). "Finally, we analyzed the LUNG CANCER EXPLORER database and found that the low expression of MIF is benefit for the survival of lung cancer." (PMID 38685050, 2024).
lung cancer (continued). "The identification of key metabolic pathways, including the novel finding of citric acid elevation and its interaction with the MIF gene, offers promising avenues for the development of targeted therapeutic strategies and the improvement of clinical outcomes for lung cancer patients." (PMID 37359381, 2023). "The identification of key metabolic pathways and the novel finding of citric acid elevation, together with its interaction with the MIF gene, provide promising directions for the development of targeted therapeutic strategies and improving clinical outcomes for lung cancer patients." (PMID 37359381, 2023). "Our findings suggest that the therapeutic effects of DCA in lung cancer may be partially mediated through the regulation of MIF expression and its interaction with citric acid." (PMID 37359381, 2023). "Further investigation of MIF as a potential therapeutic target in lung cancer is warranted." (PMID 37359381, 2023). "Furthermore, we observed a potential interaction between citric acid and the MIF gene, suggesting a novel mechanism underlying the therapeutic effects of DCA in lung cancer." (PMID 37359381, 2023). "Thus, MIF can develop into an attractive target for pharmacological intervention for the therapy of lung cancer." (PMID 33314730, 2021). "Besides, elevated expression of macrophage inhibitory factor (MIF) was detected in cisplatin resistant lung cancer cells, which mediated M2 polarization of TAMs through Src/CD155/MIF signaling." (PMID 34095111, 2021). "We hypothesized that MIF secretion may be affected by a Warburg effect involving E6 and E7 oncoproteins, as observed in lung cancer." (PMID 30634708, 2019). "We propose that dampening of the functional expression of MIF could reasonably be exploited as a clinically useful strategy in the management of many tumors including lung cancer." (PMID 23522304, 2013). "More recently, association of CD74 and MIF co-expression in lung cancers, and the identification of MIF by label-free proteomic approaches as one of many promising biomarkers in NSCLC, provides additional evidence of the importance of MIF in lung cancer development and progression." (PMID 23522304, 2013). "Targeting MIF may have clinical utility in the management of human lung cancer." (PMID 23522304, 2013). "Macrophage migration inhibitory factor (MIF) is considered a multifunctional cytokine secreted by a variety of cells such as macrophages, lymphocytes, eosinophils, epithelial cells, and endothelial cells, which importantly, is over-expressed in many different lung cancers." (PMID 23522304, 2013). "We observed that the upregulation of MIF or HIF-1α can promote the glycolysis level and cell proliferation ability of AT2 cells, but still lower than that of lung cancer cell lines." (PMID 41210694, 2025). "Our results showed that MIF promoted the increased expression of lung cancer markers, including NES and CA125, in AT II cells and carcinoid morphological changes in AT II cells, and that MIF promoted the proliferation, invasion and migration of AT II cells." (PMID 37784249, 2023). "In our in vivo lung cancer xenograft model, we observed that DCA treatment significantly reduced tumor size and suppressed MIF gene expression." (PMID 37359381, 2023). "As a high-affinity membrane receptor, CD74 is involved in multiple signaling pathways mediated by macrophage migration inhibitor (MIF), including promoting the Warburg effect by activating the NF-κB/HIF-1α pathway in lung cancer." (PMID 36358600, 2022). "Overexpression of MIF also activates NF‐κB and further upregulates HIF‐1α, thus amplifying proliferation and Warburg effect in lung cancer." (PMID 33314730, 2021). "Another effective MIF inhibitor was the isocoumarin compound SCD-19, which reduced tumor growth in a murine model of lung cancer." (PMID 32155795, 2020). "The overall survival (OS) was calculated for Src, MIF and CD155 and these three markers all predicted a poor OS in patients with lung cancer." (PMID 31036057, 2019).
lung cancer (continued). "The macrophage migration inhibitory factor (MIF) may play a role in age-related lung diseases, including lung cancer." (PMID 39195131, 2024). "In a lung carcinoma study, the individual and cooperative downregulations of MIF and DDT had a negative impact on the expression levels of VEGF and CXCL8." (PMID 36672343, 2023). "A previous study suggested that MIF overexpression could promote the Warburg effect of lung cancer cells via the NF-κB/HIF-1α signaling pathway, thus contributing to the progression of lung cancer." (PMID 36091041, 2022). "In nonsmall cell lung cancer cases there is a negative correlation between MIF mRNA and hsa‐miR‐451a, and it is discussed that low expression of hsa‐miR‐451a is associated with a negative outcome of the disease." (PMID 31701681, 2020). "The authors used an experimental setup to study lung cancer and showed that WGP-treated mouse macrophages and human monocytes exhibited a trained enhanced response upon direct contact with tumor cells or exposure to tumor-derived soluble factors, such as macrophage migration inhibitory factor (MIF)." (PMID 37069227, 2023). "However, regardless of MIF overexpression and HIF-1α activation, the glucose metabolism index levels of AT2 cells after treatment were still significantly lower than those of H1703 and Calu-3 lung cancer cell lines." (PMID 41210694, 2025).
systemic lupus erythematosus (58 papers, 2007 to 2026). An autoimmune multi-organ disease typically associated with vasculopathy and autoantibody production. "The MONICA/KORA Augsburg study reported that the MIF rs755622 C allele increased the susceptibility to juvenile idiopathic arthritis, systemic lupus erythematosus, and celiac disease associated with severe ulcerative colitis." (PMID 32560699, 2020). "Immunofluorescence analysis of renal sections obtained at the end of the study showed that miR-654 overexpression was associated with a decline in MIF expression in lupus glomeruli." (PMID 31608058, 2019). "Here, using single-cell transcriptomics and a lupus-prone mouse model, we identify keratinocyte-derived macrophage migration inhibitory factor (MIF) as a key amplifier of cutaneous inflammation through a self-sustaining feedback loop." (PMID 41629274, 2026). "Inhibition of MIF and knockdown of CD74 protect against glomerulonephritis in lupus-susceptible mice." (PMID 36445632, 2023). "On the other hand, it has been reported that MIF is upregulated and plays a role in infectious diseases, inflammatory diseases such as sepsis, asthma, arteriosclerosis, lupus, acute respiratory distress and numerous cancer types." (PMID 36298774, 2022). "In patients with active SLE, elevated serum and urinary MIF levels are detected in lupus patients and positively correlated with the severity of LN." (PMID 35563296, 2022). "In systemic lupus erythematosus (SLE), higher expression MIF alleles (173C and 794 extended alleles) were associated with a lower disease risk." (PMID 33842495, 2021). "Glomerular injury and renal disease manifestations are reduced in MRL/lpr Mif−/− mice, and pharmacologic MIF antagonists protect against glomerulonephritis in lupus-prone MRL/lpr or NZB/NZW F1 mice." (PMID 31608058, 2019). "As in our study, miR-654 showed the most powerful ability to inhibit the expression of MIF among candidate miRNAs, we focused on its potential role in pro-inflammatory pathways relevant to lupus." (PMID 31608058, 2019). "Activation of miR-654 reduced IL-1β, IL-6, IL-8, and TNF-α production, reduced gomerulonephritis, and decreased MIF, IgG, and C3 expression in murine lupus glomeruli." (PMID 31608058, 2019). "The aim of this study was to investigate the associations of serum concentrations of MIF and a marker of Type I IFN activity with ethnicity and measures of disease severity, in a prospective, multi-ethnic lupus cohort." (PMID 27453287, 2016). "Polymorphism of MIF on the −173 position has been reported in several diseases, including juvenile idiopathic arthritis (JIA), multiple sclerosis, systemic lupus erythematosus (SLE), and ulcerative colitis." (PMID 25821795, 2015). "Functional polymorphisms in the MIF gene promoter have been studied in autoimmune diseases such as juvenile inflammatory arthritis, rheumatic arthritis, scleroderma, and systemic lupus erythematosus (SLE)." (PMID 23721694, 2013). "Leng and colleagues reported that a small-molecule MIF antagonist protects against glomerulonephritis in lupus-prone NZB/NZW F1 and MRL/lpr mice." (PMID 22551315, 2012). "In the lupus-prone mice, it has been demonstrated that renal MIF expression was significantly higher in MRL/lpr mice compared with nondiseased control mice." (PMID 22046508, 2010). "Foote and colleagues recently reported increased MIF levels and a correlation with the disease activity in patients with systemic lupus erythematosus." (PMID 17470266, 2007). "Study has shown that MIF antagonism reduces both the functional and histological indices of glomerulonephritis, as well as the expression of inflammatory cytokines and chemokines, in lupus-prone MRL/lpr or NZB/NZW F1 mice." (PMID 39081313, 2024).
systemic lupus erythematosus (continued). "Evidence of MIF in T cell-mediated kidney disease comes from the observation that T cell-mediated renal injury is prevented in lupus-prone mice targeted for the deletion of MIF, whereas treatment with anti-MIF antibody protects against macrophages and T cell-mediated anti-GBM crescentic GN." (PMID 35563296, 2022). "MIF inhibition and CD74 deficiency protected against glomerulonephritis in lupus-prone mice." (PMID 32655566, 2020). "In agreement with this hypothesis, an immunomodulatory peptide, hCDR1, which reduces NPSLE-like symptoms in lupus-prone mice, has been found to act on the MIF pathway by reducing its overexpression in the hippocampus." (PMID 30428632, 2018). "In addition, recent developments in the understanding of the role of MIF in systemic lupus erythematosus (SLE) are reviewed." (PMID 26617609, 2015). "Previous results showing increased levels of MIF in patients with systemic lupus erythematosus could partly be explained by corticosteroid use." (PMID 17470266, 2007). "Recently, Phase I and Phase II studies have been carried out with specific MIF monoclonal antibodies in patients with cancer and systemic lupus erythematosus (SLE), and can also be tested in patients with BLEL." (PMID 30348174, 2018). "In the lupus-prone MRL/lpr mouse strain, MIF expression has been demonstrated to be increased in both skin and kidney lesions." (PMID 26617609, 2015). "It is also well defined that MIF is pathogenic in immunologically-mediated kidney disease as mice lacking MIF are protected against lupus mice and anti-GBM GN." (PMID 38846956, 2024). "In addition, there are a large number of studies that have showed that elevated levels of MIF can be detected in patients suffering from various inflammatory and autoimmune conditions, such as RA and systemic lupus erythematosus (SLE)." (PMID 35465102, 2022). "Recently it has been suggested that MIF is a critical effector of organ injury in systemic lupus erythematosus in the absence of major changes in T-cell and B-cell markers or alterations in autoantibody production." (PMID 17470266, 2007). "Similarly, renal MIF is increased in patients with lupus (and non-lupus) proliferative glomerulonephritis, correlating with leukocyte infiltration, tissue damage and impairment of renal function." (PMID 26617609, 2015). "Thus, it is likely that PUFAs and their anti-inflammatory products such as lipoxins, resolvins, protectins and maresins inhibit the production of various pro-inflammatory molecules including MIF and HMGB1 and thus, suppress inflammation in diseases such as lupus and rheumatoid arthritis." (PMID 21569625, 2011). "Serum MIF and DDT were quantified in 105 SSc patients by ELISA and levels compared to healthy controls (HC) and patients with systemic lupus erythematosus (SLE)." (PMID 30546906, 2018). "In lupus-prone mouse strains, the upregulation of MIF and CD74 was also positively correlated with worsening renal inflammation, whereas lupus mice lacking the MIF or CD74 receptor are protected from LN, demonstrating the role of the MIF-CD74 axis in the pathogenesis of LN." (PMID 35563296, 2022).